CUX1 (cut like homeobox 1)
Diseases named in the same sentence as CUX1 in open-access papers (continued):
Sharing a sentence is not in itself a finding about the gene and the disease.
tumor (continued). "In contrast, in tumor samples and in cell lines derived from MMTV-p200 tumors, we observed expression of a CUX1 protein of apparent M.W. of 200 kDa as well as many bands of lower M.W. including a species migrating at 110 kDa (lanes 1, 2, 5, 6, 7, 8)." (PMID 24618719, 2014). "Both CUX1 and SP3 are key regulators of tumor aggressiveness." (PMID 40095604, 2025). "In vitro and in vivo, we could show that the p110 CUX1 variant, resulting from proteolytic cleavage of full-length p200 CUX1 by cathepsin L, was active in PDAC and enhanced tumor development in concert with oncogenic Ras." (PMID 34070180, 2021). "In summary, we identified the transcription factor CUX1 as mediator of tumour progression in non-functional PanNET in vitro and in vivo, indicating that the CUX1-dependent signalling network is a promising target for future therapeutic intervention." (PMID 32707646, 2020). "They demonstrated that the full-length CUX1 interacts with NF-κB p65 and HDAC1 to form a protein trimer to repress NF-κB signaling in TAMs, resulting in inhibition of M1 polarization and enhanced angiogenesis and tumor progression." (PMID 32547943, 2020). "Our current study extends these findings to non-functioning PanNET indicating that CUX1 is an important mediator of progression, and serves as potential predictive biomarker for resistance to cytotoxic chemotherapy in this tumour entity." (PMID 32707646, 2020). "Furthermore, two large-scale deletions in our dataset overlap known tumor suppressors, PIK3R1 and CUX1, and are likely drivers." (PMID 32697969, 2020). "Lentivirus‐mediated knockdown of circ‐CUX1 significantly reduced the growth, tumor weight, Ki‐67 proliferation index, and CD31‐positive microvessels of subcutaneous xenograft tumors, with altered expression of circ‐CUX1 target genes." (PMID 31709724, 2019). "CUX1 p110/90 isoforms havebeen shown to bind Snail promoter to increase it transcription and bind E-cadherinpromoter to repress its transcription leading to increased EMT, tumor migration andinvasion." (PMID 30964885, 2019). "Meanwhile, stable knockdown of circ‐CUX1 led to decrease in CUX1 promoter activity and expression of p200 and p110 in tumor cells, without effects on CUX1 mRNA stability or CASP levels (Figs EV2A–D and 2H)." (PMID 31709724, 2019). "To investigate whether higher CUX1 expression would increase resistance to radiation, we established populations of Hs578T, DLD-1 and T98G tumor cells stably carrying either a retroviral vector expressing p200 CUX1 or an empty vector." (PMID 28147323, 2017). "Closer examination of the results, however, revealed a more complex situation since CUX1 knockdown also reduced clonogenic efficiency in the absence of radiation in 7 out of 9 tumor cell lines: Hs578T, MDA-MB-231, HT29, DLD-1, HCT116, T98G and HCC827." (PMID 28147323, 2017). "Moreover, while the stimulation of proliferation, cell motility, and resistance to apoptosis provide mechanisms by which CUX1 may contribute to tumorigenicity, we have yet to identify a molecular function that could explain the status of CUX1 as a haplo-insufficient tumor suppressor gene." (PMID 24618719, 2014). "Although this finding is consistent with the fact that CUX1 activates Lats1 transcription, there is an apparent discrepancy between the elevated expression of Lats1 in tumors from transgenic mice and the purported role of LATS1 as a tumor suppressor." (PMID 19656388, 2009). "In contrast to solid tumors and for reasons not entirely understood, CUX1 may act as tumor suppressor in myeloid malignancies in which it is frequently inactivated." (PMID 34070180, 2021). "Because most of the short isoforms are derived from the full-length CUX1 transcript, RNAi approach is not able to specifically knock down indicated isoforms, which makes RNAi not suitable to determine the roles of full-length CUX1 and its isoforms in tumor progression." (PMID 32547943, 2020).
tumor (continued). "Notably, circ‐CUX1 bound to RRM region of EWSR1, resulting in EWSR1‐mediated MAZ transactivation, suggesting the oncogenic roles of circ‐CUX1/EWSR1/MAZ axis in aerobic glycolysis and tumor progression." (PMID 31709724, 2019). "It remains to be demonstrated whether the DNA repair function of CUX1 contribute to its role as a tumor suppressor, however, it is clear that RAS-driven cancer cells exploit this function of CUX1 to avoid senescence and continue to proliferate in spite of elevated levels of reactive oxygen species." (PMID 25682875, 2015). "However, none of the reported functions of CUX1 in stimulating cell cycle progression, cell proliferation, cell motility, and resistance to apoptosis is consistent with a role as a tumor suppressor." (PMID 24618719, 2014).
cancer (65 papers, 2007 to 2025). A tumor composed of atypical neoplastic, often pleomorphic cells that invade other tissues. "Some studies have found that diminished CUX1 expression is implicated in cancer development, suggesting a protective role when fully expressed." (PMID 38659042, 2024). "CUX1 can regulate motility-associated gene expression to stimulate cancer migration and invasion, such as Wnt/β-catenin, snail, and slug." (PMID 33014778, 2020). "Specifically, gain-of-function as well as loss-of-function studies have shown that increased CUX1 activity significantly enhanced cell sensitivity and cancer tissue response to chemotherapy drugs and resulted in increased apoptosis and growth inhibition." (PMID 29686393, 2018). "A previous study showed that the synthetic lethality of CUX1 knockdown in RAS-driven cancer cells was associated with an increase in oxidative DNA damage caused by high levels of reactive-oxygen species (ROS)." (PMID 28147323, 2017). "Recently, mutations in CUX1 have been identified in 20 different carcinoma types, making this gene an important candidate for tumorigenesis." (PMID 28139749, 2017). "Recently, it was shown that, by integrating SB TMIM in mice and mutation analysis of human cancer genomes, loss of function of the transcription factor CUX1 drives myeloid malignancy and other cancer types." (PMID 26481584, 2015). "While CUX1 is the target of monoallelic deletion or inactivating somatic mutations in many cancers, increased CUX1 expression is associated with shorter disease-free survival." (PMID 25682875, 2015). "The Cut homeobox 1 (CUX1) gene is a target of loss-of-heterozygosity in many cancers, yet elevated CUX1 expression is frequently observed and is associated with shorter disease-free survival." (PMID 24618719, 2014). "Expression of p110 and p75 CUX1 in transgenic mice increases the susceptibility to cancer in various organs and tissues." (PMID 19656388, 2009). "In addition, CUX1 has been associated with tumorigenesis in some cancers and alcohol is considered a risk factor for multiple cancers." (PMID 41153338, 2025). "In particular, we found the presence of transcripts, such as Cux1 and Arpc2, which variably regulate DNA replication, cell proliferation and motility and Csnk1e, which is implicated in the Wnt/β-catenin pathway, a key determinant in cancer proliferation." (PMID 39061080, 2024). "Indeed, CUX1 inactivating mutations and loss of heterozygosity have been identified as contributing factors in various human cancers." (PMID 37744879, 2023). "There is contradictory evidence between the association of CUX1 and cancer." (PMID 32180898, 2020). "Analysis of human cancer datasets confirms that elevated WNT gene expression is associated with high levels of CUX1 and GLIS1 and correlates with genes of the epithelial-to-mesenchymal transition (EMT) signature: VIM, SNAI1 and TWIST1 are elevated whereas CDH1 and OCLN are decreased." (PMID 25217618, 2014). "Among them, CUX1, IKZF3, and NR4A1 (highlighted in red in the figure) are well-documented cancer-associated factors." (PMID 40923764, 2025). "Among the cancer drivers that show the biggest association changes between CMS2 and CMS4, we found HIF1A and CUX1, both of which are implicated in tumorigenesis and progression, and GATA4, which controls senescence." (PMID 41114645, 2025). "Conversely, evidence also indicates that elevated CUX1 expression can advance cancer progression, underscoring its complex involvement in oncogenesis." (PMID 38659042, 2024). "This study marks the first to elucidate the oncogenic function of CUX1 within the context of OS cells, revealing that silencing CUX1 can mitigate the cancer-promoting effects attributed to circ_0076684." (PMID 38659042, 2024). "We found that a small number of genes (e.g., RET, RECQL4, CUX1, FGFR4, PIK3R1, FGFR3, and GNAS) had some co-occurring variants per patient in different cancer types." (PMID 38637555, 2024).
cancer (continued). "The initial indication of CUX1 role in cancer arose from observations of its overexpression in primary tumors and cancer cell lines." (PMID 37744879, 2023). "CUX1 is located on human chromosome 7q22 and is frequently rearranged in cancers, while CUX2 is on chromosome band 12q24.11-q24.12." (PMID 35546872, 2022). "CUX1 has also been shown to undergo inactivating mutations and loss of heterozygosity (LOH) in a number of human cancers." (PMID 35546872, 2022). "These cancer cells can adapt by increasing their capacity to repair oxidative DNA damage in part through elevated expression of CUT domain proteins such as CUX1, CUX2, or SATB1." (PMID 34204734, 2021). "CUX1 suppressed the caspase-9 and -3 axis, well-known key effectors of the apoptosis-machinery in cancer in all examined cell lines." (PMID 32707646, 2020). "CUX1 belongs to the homeodomain transcription factor family, And its involvement in the proliferation and progression of several cancers has been proved." (PMID 33344221, 2020). "CUX1 has been described as a transcriptional activator as well as a repressor, but its cancer-promoting effects have garnered increased research interest." (PMID 33344221, 2020). "CUX1 was chosen for further clinical and functional analysis because it is involved in cellular processes relevant to cancer including cell proliferation, cell motility and invasiveness." (PMID 32180898, 2020). "Tube formation assay showed that cancer cells treated with medium preconditioned by CUX1-knockdown, significantly suppressed angiogenesis capabilities." (PMID 33344221, 2020). "Our present study shows that TNBC cellsand patient cancer tissue have higher Cat L expression/ activity and CUX1 expressioncompared to normal or ER-positive cells." (PMID 30964885, 2019). "On the other hand, higher CUX1 expression in RAS-driven cancer cells that produce elevated levels of reactive oxygen species enables rapid repair of oxidative DNA damage, thereby preventing cellular senescence and allowing proliferation." (PMID 28147323, 2017). "We found that CUX1 knockdown sensitizes cancer cells to radiation, whereas overexpression confers resistance." (PMID 28147323, 2017). "In the present study, we investigated the role of CUX1, in particular its DNA repair function, in the resistance of cancer cells to ionizing radiation." (PMID 28147323, 2017). "Cancer cell survival following ionizing radiation is reduced by CUX1 knockdown and increased by higher CUX1 expression." (PMID 28147323, 2017). "In summary, our results have uncovered the requirement for CUX1 expression in cancer cells with elevated ROS levels." (PMID 28147323, 2017). "Recent studies have reported that transcription factors such as Foxo3 and Cux1 are involved in the regulation of Pik3ip1 expression in brain tissue and cancer cells." (PMID 25826393, 2015). "Elevated CUX1 mRNA and protein expression was reported in primary tumors and cancer cell lines of various types." (PMID 19656388, 2009). "In the FVB genetic background, multiparous transgenic mice carrying a p75 or p110 CUX1 transgene developed malignancies in the mammary gland and other tissues, with a penetrance of approximately 50%." (PMID 19656388, 2009). "While inactivation of Lats1/wts in mouse and Drosophila can increase cancer incidence, results from the present study demonstrate that Lats1 is a transcriptional target of CUX1 that can be overexpressed in tumors of various tissue-types." (PMID 19656388, 2009). "Therefore, we conclude that circ_0076684 contributes to OS progression through its regulatory effect on CUX1 expression, highlighting a novel aspect of CUX1's multifaceted role in cancer biology." (PMID 38659042, 2024). "Cut-like homeobox 1 (CUX1), the transcription factor involved in embryonic development, could regulate the cancer cell proliferation, migration, and EMT." (PMID 37599427, 2023).
cancer (continued). "Top expressed cancer-implicated gene targets for each TF converged on notable genes involved in cell signaling (SMAD3, PTPRJ), BCL6 regulation (FBXO11, BCOR), and transcriptional regulation (RUNX1, ERG, CUX1)." (PMID 38116118, 2023). "Additionally, a recent study reported the inability to detect p75 CUX1 in cancer cells, further emphasizing the need for careful interpretation of CUX1 isoform functions in diverse tissues." (PMID 37744879, 2023). "Studies in human cancers show that CUX1 is overexpressed in over 70% of cancers." (PMID 36176767, 2022). "CUX1 is expressed in many cell types and organs, including the lung, and is involved in diverse processes, such as cell migration, cell adhesion and motility and it is involved in brain and liver development and cancer." (PMID 35615634, 2022). "Strikingly, however, knockdown of CUX1 or SATB1 sensitized all tested cancer cell lines to ionizing radiation, whether they displayed high ROS levels or not." (PMID 36176767, 2022). "Moreover, the resistance of cancer cells to cisplatin treatment was decreased by CUX1 knockdown but increased by ectopic expression of the two CUT domains." (PMID 36176767, 2022). "Interestingly, CUX1 gene copy number is increased in over 70% of human cancers, and its expression inversely correlates with patient survival." (PMID 33069104, 2021). "CUX1 knockdown was lethal to cancer cells following ionizing radiation." (PMID 33069104, 2021). "Next to MSH6 and MUTYH, CUX1 has been described as a cancer‐driving gene." (PMID 32615015, 2020). "The role of CUX1 in cancer is complex and still controversial." (PMID 33014778, 2020). "Most studies to date have attributed an oncogenic role for CUX1 in human cancer." (PMID 32180898, 2020). "Recently, studies have reported that the overexpression and activation of CUX1 may have a crucial impact on promoting cancer cell growth, invasion, and metastasis." (PMID 33344221, 2020). "Interestingly, the cell death regulatory role of Cut is conserved in vertebrates, and Cux1 human cancer cells show apoptotic defects." (PMID 29854765, 2018). "However, CUX1 knockdown is sufficient by itself to reduce viability in many cancer cell lines that exhibit high levels of reactive oxygen species (ROS)." (PMID 28147323, 2017). "Together these results suggest that the direct role of CUX1 proteins in DNA repair may influence the extent to which cancer cells exhibit resistance to radiation." (PMID 28147323, 2017). "The molecular functions of CUX1 that explain its dual role in cancer remain to be clarified." (PMID 28147323, 2017). "Similarly, CUX1 belongs to this class of cancer genes that can both protect against cancer and promote cancer development and progression depending on physiological context." (PMID 25682875, 2015). "In addition to their well-established role in development and differentiation, there are also several examples linking the vertebrate Cut homologue Cux1 to apoptosis and cancer." (PMID 22438831, 2012). "A third isoform, p75 CUX1, is generated from a shorter mRNA that is initiated within intron 20 and whose expression is restricted to certain cell-types and was found to be activated in some human breast tumors and cancer cell lines." (PMID 19656388, 2009). "Thus, in cancers with chromosome 7 copy number gains, the driver may be a true oncogene, while CUX1 is a passenger." (PMID 34997000, 2022). "In addition, CUX1 knockdown was lethal in human cancer cells expressing oncogenic RAS." (PMID 34070180, 2021). "circ-CUX1 knock-down inhibits aerobic glycolysis, proliferation, progression, and aggressiveness of NB. circ-CUX1 binds to EWSR1 to enable its contact with MAZ, leading to transactivation of MAZ and transcriptional modification of CUX1 and other genes linked with cancer progression." (PMID 33718173, 2021).